PA2G4 (proliferation-associated 2G4)
Diseases named in the same sentence as PA2G4 in open-access papers (continued):
Sharing a sentence is not in itself a finding about the gene and the disease.
type 1 diabetes (1 paper, 2023). "PA2G4 was also evaluated as a potential biomarker in the serum of type 1 diabetes patients." (PMID 36769128, 2023).
cancer (19 papers, 2012 to 2025). A tumor composed of atypical neoplastic, often pleomorphic cells that invade other tissues. "The role of proliferation associated protein 2G4 (PA2G4) in tumorigenesis and cancer progression has been widely investigated in various cancers." (PMID 35526051, 2022). "Our findings suggest that the three cancer-associated gene expression regulators, PA2G4, PTTG1 and YB-1, play important roles in progression of HCC." (PMID 33379356, 2020). "Human Ebp1 is a member of the proliferation-associated 2G4 (PA2G4) family and plays an important role in cancer regulation." (PMID 32034140, 2020). "While our findings highlight the therapeutic potential of targeting PA2G4 in MYC-driven cancers, several important limitations remain." (PMID 41002386, 2025). "Ultimately, understanding the structural basis of PA2G4′s oncogenic function will be essential for developing potent and selective inhibitors that disrupt its role in cancer while minimizing effects on its physiological functions." (PMID 41002386, 2025). "Our study builds on this emerging evidence and further supports PA2G4 as an oncogenic cofactor in MYC-driven cancers." (PMID 41002386, 2025). "We demonstrate that PA2G4 stabilizes c-MYC in cancer cells, thereby expanding the landscape of MYC-interacting proteins that can be exploited for therapeutic intervention." (PMID 41002386, 2025). "While the roles of Pa2G4 in cancer and other diseases have been extensively studied, few reports have addressed its role in embryonic development." (PMID 39496919, 2024). "In summary, GNL3 and PA2G4 play crucial biological roles in cancer, supporting important cellular processes such as cell migration, proliferation, apoptosis, and tumor growth." (PMID 37345060, 2023). "PA2G4 exerts versatile functions in cancer cells, we doubted the possibility of its role as “housekeeping gene” in some cancer biological behaviors." (PMID 35526051, 2022). "Taken together, these results revealed a critical role of PA2G4 in cancer progression, and especially metastasis." (PMID 35526051, 2022). "pa2g4 (aka ebp1) is expressed in craniofacial tissues and cancers, and its protein binds to Six1 to regulate the development of neural crest and PPE." (PMID 34208995, 2021). "In contrast, the analysis of the Cancer Genome Atlas RNAseq dataset reported that the expression level of PA2G4 positively correlated with that of the pseudogene, as they were both up regulated in most of the tumors analyzed including BlCas." (PMID 32244410, 2020). "Our approach using distinct cell lines identified characteristic APA profile changes in several cancer relevant genes including SMAD3, PA2G4 and MTHFD1L and linked the latter two to the de-regulation of hnRNPC in metastatic site-derived cells." (PMID 31147722, 2019). "Targeting the PA2G4–MYC axis represents a promising therapeutic strategy for MYC-driven cancers." (PMID 41002386, 2025). "Although the role of Pa2G4 in cancer and mammalian cell model systems has been extensively studied, a potential function for Pa2G4 in ciliogenesis remains unknown." (PMID 39496919, 2024). "Collectively, chemical inhibition of PA2G4-MYCN binding by WS6 analogues represents a first-in-class drug discovery which may have implications for other MYCN-driven cancers." (PMID 36980710, 2023). "PA2G4 is intensively involved in tumorigenesis and cancer progression." (PMID 35526051, 2022). "The role of PA2G4 has been intensively investigated in multiple cancer types." (PMID 35526051, 2022). "In our study, we showed that PA2G4 enhanced the migration and invasion ability of cancer cells, induced a rearrangement of F-actin and modulated the expression of EMT-related molecular markers (E-cadherin, N-cadherin, occluding, Vimentin, α-SMA and ZO-1) as well as TFs (ZEB1, ZEB2 and Snail)." (PMID 35526051, 2022). "The functions of PA2G4 in cancers are highly context dependent." (PMID 35526051, 2022).
cancer (continued). "Future studies will focus on elucidating the precise mechanism by which PA2G4 regulates MYC stability, including evaluation of MYC phosphorylation status and its regulation via the proteasome pathway in PA2G4-deficient and -proficient contexts across multiple cancer types." (PMID 41002386, 2025). "In summary, our study identifies PA2G4 as a novel and critical regulator of MYC protein stability, establishing it as a promising therapeutic target in MYC-driven cancers." (PMID 41002386, 2025). "Our study provides novel insights into the role of PA2G4 as a critical regulator of c-MYC stability and underscores its potential as a therapeutic target across MYC-driven cancers." (PMID 41002386, 2025). "Mechanistically, we demonstrated that PA2G4 is essential for maintaining c-MYC protein stability and cell viability across various c-MYC-expressing cancer cell lines." (PMID 41002386, 2025). "We have identified a protein called PA2G4, which is a cofactor for MYCN in promoting cancer cell growth." (PMID 36980710, 2023). "Through analysis of PA2G4 abundances in 28 pairs of GBC and para-cancer tissues by western blot, we found that p48 isoform increased remarkably in GBC tissues, while p42 was usually undetectable." (PMID 31752867, 2019). "Together, these findings identify PA2G4 as a shared cofactor for both the c-MYC and MYCN oncoproteins and highlight its interaction with MYC family oncoproteins as a promising therapeutic vulnerability in MYC-driven cancers." (PMID 41002386, 2025). "In cancers where MYC plays a critical role in tumor growth and chemoresistance, combining PA2G4 inhibition with chemotherapy could provide a more effective strategy for overcoming drug resistance and improving patient outcomes." (PMID 41002386, 2025). "Given our findings that PA2G4 and c-MYC form a positive forward feedback expression loop in MYC- and MYCN-driven cancers, we hypothesized that WS6 would repress the expression of both proteins in c-MYC-driven malignant cells." (PMID 41002386, 2025). "Furthermore, based on the mechanism driving efficacy upon HDAC inhibition, our work positions PA2G4 as a druggable target for a neglected population with EVI1-expressing AML and potentially for other Myc-dependent cancers." (PMID 38834613, 2024). "PA2G4, also designated ErbB3 receptor binding protein 1 (EBP1), is a well-conserved DNA/RNA binding protein that modulates transcriptional activity in different cancer cell types." (PMID 33379356, 2020). "Interestingly, we found that in GBC tissues, but not para-cancer tissues, the expression level of circERBB2 was positively correlated with abundance of PA2G4 protein, suggesting that circERBB2 promoted GBC progression in synergy with PA2G4." (PMID 31752867, 2019).
tumor (17 papers, 2012 to 2025). "When more MYCN is present, knockdown of both alleles of PA2G4 is required for inhibition of tumor development." (PMID 41002386, 2025). "By demonstrating that disruption of PA2G4 impairs MYC stability and tumor cell viability, we provide a compelling rationale for targeting the PA2G4–MYC axis as an alternative to direct MYC inhibition." (PMID 41002386, 2025). "We demonstrate that PA2G4 promotes MYCN-driven tumor growth in vivo and stabilizes c-MYC protein by preventing its proteasomal degradation." (PMID 41002386, 2025). "Kaplan–Meier analysis indicated that HCC patients with higher expression of PA2G4 exhibited worse overall survival and higher tumor recurrence rates." (PMID 35526051, 2022). "Expression levels of PA2G4P4 were positively correlated with those of PA2G4 in all tumor types except KIRC, PRAD, and THCA – remarkable given that PA2G4 is on chromosome 12 and PA2G4P4 is on chromosome 3." (PMID 28673244, 2017). "However, in hemizygous Th-MYCN mice, a single allele knockout was sufficient to prolong survival, suggesting a gene dosage effect between MYCN and PA2G4 in driving tumor progression." (PMID 41002386, 2025). "In humans, two splicing variants with opposite functions have been described: the long PA2G4, which suppresses apoptosis and promotes cell growth, acting as an oncogene, and the short one, which functions as a tumour suppressor, promoting cell differentiation and suppressing proliferation." (PMID 38651369, 2024). "PA2G4, the gene encoding EBP1, is mutated at a very low frequency (0.24% in all tumours)." (PMID 27118868, 2016). "Additionally, MDK (3.99), NME1 (4.82), and PA2G4 (4.21) showed increased expression in the tumor tissues from the patients with recurrent HCC." (PMID 24377043, 2013). "We have developed a compound WS6 and its analogous, which inhibits PA2G4 and MYCN protein levels and reduces tumour cell growth." (PMID 36980710, 2023). "The relationship between PA2G4 and MYC remains less clear, particularly in contexts where MYC expression is low, and may depend on tumor subtype." (PMID 41002386, 2025). "Hemizygous Th-MYCN+/− mice had a survival probability of 30% when the PA2G4 gene was wildtype, whereas both hemizygous PA2G4WT/DelEx1–5 and homozygous PA2G4DelEx1-/DelEx1–5 knockout equally increased tumor-free survival probability of the homozygous Th-MYCN+/+ mice to 80%." (PMID 41002386, 2025).
PA2G4 also shares sentences with these, for which no sentence is quoted: infection (3 papers); nasopharyngeal carcinoma (2); acute lymphoblastic leukemia (1); adenoid cystic carcinoma (1); Alzheimer disease (1); atrial fibrillation (1); bladder cancer (1); cardioembolic stroke (1); cardiovirus infection (1); chronic hepatitis B virus infection (1); malignant melanoma (1); medulloblastoma (1); myeloma (1); oral squamous cell carcinoma (1).